IGFBP3 (insulin like growth factor binding protein 3)
Diseases named in the same sentence as IGFBP3 in open-access papers (continued):
Sharing a sentence is not in itself a finding about the gene and the disease.
lung carcinoma (continued). "Elevated plasma levels of IGF-I have been associated with an increased risk of lung cancer, and high plasma levels of IGFBP-3 associated with a reduced risk." (PMID 19549343, 2009). "In summary, we found that association between circulating levels of IGF-I, IGFBP-3 and the risk of lung cancer are marginally and statistically significant, respectively." (PMID 19549343, 2009). "Here we performed a systematic meta-analysis of all studies published to date to determine and assess the strength of the association between circulating levels of IGF- I and IGFBP-3 and lung cancer." (PMID 19549343, 2009). "Recently, many large-scale clinical prospective case-control studies on association between circulating levels of IGF-I, IGFBP-3 and the risk of lung cancer were performed." (PMID 19549343, 2009). "With regard to the association between IGFBP-3 and lung caner, the data suggests IGFBP-3 acts as a tumor suppressor and has a inverse correlation with the risk of lung cancer, and it does have statistical significance." (PMID 19549343, 2009). "Studies have found that high IGF-1 levels in the blood may increase the risk of lung cancer, while high levels of circulating IGFBP-3 may decrease risk." (PMID 38540176, 2024). "IGFBP-3 might be also considered a potential diagnostic and prognostic biomarker in the treatment of bone metastases in lung cancer." (PMID 37510722, 2023). "IGFBP-3 has been shown to have an inverse correlation with the risk of lung cancer." (PMID 36428962, 2022). "Disruption of IGFBP-3 at transcriptional and post-translational levels has been implicated in the pathophysiology of many different types of cancer including breast, prostate, and lung cancer." (PMID 32443727, 2020). "High levels of circulating IGF-1 may increase lung cancer risk, while high levels of IGFBP-3 may reduce the risk of lung cancer." (PMID 28885346, 2017). "But the circulating concentration of IGFBP-3 was showed to inversely associate with lung cancer." (PMID 23185474, 2012). "We also assumed that there would be a conceivable time point that the concentration of circulating IGFBP-3 could participant in helping us to distinguish the status of people into high lung cancer risk and low lung cancer risk groups." (PMID 23185474, 2012). "Heavy smokers carrying susceptible IGF1, IGF2, and IGFBP3 have a higher risk of lung cancer." (PMID 22347413, 2012). "We could see inverse relationship between the circulating concentration of IGFBP-3 and lung cancer risk." (PMID 23185474, 2012). "However, we did not observe an independent relationship between the IGF2 and IGFBP3 polymorphisms and risk of lung cancer." (PMID 22347413, 2012). "High serum levels of IGFBP-3 associated with a reduced lung cancer risk." (PMID 19549343, 2009). "However, IGF1, IGF2, and IGFBP3 may be susceptibility genes for lung cancer only in certain ethnic populations." (PMID 22347413, 2012). "Therefore, tea polyphenols may decrease lung cancer risk by increasing IGFBP3 levels and lowering IGFs." (PMID 22347413, 2012). "Collectively, we revealed that FTO drives lung cancer progression via m6A‐dependent sequestration of IGFBP3 mRNA into P‐bodies by IMP3, which suppresses translation and activates AKT signalling." (PMID 40621649, 2025). "In the context of lung cancer, we observed that IGFBP3 overexpression enhanced the activity of AKT, as shown by elevated phosphorylation at S473 and T308." (PMID 40621649, 2025). "To investigate the role of FTO‐mediated regulation of IGFBP3 in lung cancer progression, we first compared FTO and IGFBP3 transcript levels in paired tumour and adjacent normal tissues from 36 LUAD patients." (PMID 40621649, 2025). "In A549 cells, heparanase exhibited opposite actions with IGFBP3, a potential protective factor in lung cancer." (PMID 41031217, 2025). "provided evidence that overexpression of IGFBP-3 can induce cell apoptosis and enhance the cisplatin response in lung cancer." (PMID 38822233, 2024).
lung carcinoma (continued). "For instance, high serum IGF-1 and IGFBP-3 levels raise the risk of numerous cancers; however, in a meta-analysis, IGFBP-3 decreased the risk of lung cancer." (PMID 38928185, 2024). "IGFBP3-overexpressing lung cancer cells showed higher sensitivity to cisplatin, resulting in attenuated cancer progression 32-34." (PMID 38169528, 2024). "IGFBP-3 expression was found earlier to be significantly diminished in cisplatin-resistant lung cancer cells." (PMID 36766747, 2023). "Similar to IGF-I, no consensus was maintained among the accounts concerning how IGFBP-3 affects the development of lung cancer." (PMID 35198099, 2022). "A synopsis of the results stipulates IGF-I generally increases with lung cancer, especially individuals diagnosed with advanced disease, while IGFBP-3 decreases." (PMID 35198099, 2022). "An inverse relationship between IGFBP-3 and lung cancer in ever-smokers was offered in two papers, whereas another investigation revealed augmented IGFBP-3 correlated with advancement of lung cancer." (PMID 35198099, 2022). "Trials that concerned IGFBP-3 typically described lower levels of the binding protein in all lung cancers." (PMID 35198099, 2022). "Another meta-analysis of 2686 lung cancer patients examined common polymorphisms within the IGF axis, finding that certain patients had a predisposition to lung cancer due to genetic variations in IGF-I, IGF-II, IGF-1R, IGFBP-3, and IGFBP-5." (PMID 35198099, 2022). "The analysis did, however, indicate a statistically significant, inverse relationship between IGFBP-3 levels and the existence of lung cancer." (PMID 35198099, 2022). "Humanin has been shown to bind to IGFBP-3 and inhibit nuclear translocation and induction of apoptosis of IGFBP-3 in human lung cancer cells by suppressing the IGFBP-3 interaction with importin-β." (PMID 32443727, 2020). "First, insulin-like growth factor-binding protein 3 (IBP3) has been reported to be a lung cancer biomarker in serum, bronchoalveolar lavage fluid and lung tissue and has also been reported to modulate lung tumorigenesis." (PMID 32678190, 2020). "Previous studies have reported that IGFBP3 expression is increased in many tumors with metastasis, including lung cancer and oral cancer." (PMID 32703944, 2020). "IGFBP3 up-regulation in lung cancer cells leads to increased MET expression via Smad2/3 activation and results in EGFR- and Met-TKI dual resistance." (PMID 30609749, 2019). "Exposure to sodium arsenite decreased gene expression of IGFBP3 in A549 human lung cancer cells and human normal (hEp), premalignant (SCC12F2) and malignant (SCC9) keratinocytes." (PMID 29947889, 2018). "We further reported that hypermethylation of the IGFBP-3 promoter is a frequent abnormality in NSCLC, which is one mechanism that silences IGFBP-3 expression in lung cancers, particularly NSCLC." (PMID 25944691, 2015). "Regardless, heavy smoking in cumulative dose would likely increase lung cancer risk by increasing carcinogen exposure long-term, while simultaneously increasing IGF1 or IGF2 levels or decreasing IGFBP3 levels." (PMID 22347413, 2012). "Circulating IGFBP-3 status detected years before the diagnosis of lung cancer was within the normal range; however, the circulating IGFBP-3 status of the confirmed lung cancer patients was lower than normal range." (PMID 23185474, 2012).
lung carcinoma (continued). "In another word, the lung cancer patients were statistically demonstrated to have lower levels of circulating IGFBP-3 compared with control participants, which suggested IGFBP-3 a promising candidate for the biomarkers of lung cancer." (PMID 23185474, 2012). "Then, we examined the effect of IGFs and IGFBP3 on lung cancer stratified by habits of green tea consumption." (PMID 22347413, 2012). "Efforts have been made expecting to prove the clinical significance of circulating IGF-1 and IGFBP-3 in cancers by evidence-based methods, among which lung cancer is a magnificent being." (PMID 23185474, 2012). "Standard mean difference (SMD) was also calculated to indicate the difference of the circulating IGF-1 and IGFBP-3 concentrations between the lung cancer case group and the control group." (PMID 23185474, 2012). "Since circulating IGF-I and IGFBP-3 remain important factors in lung cancer, more studies need to be conducted to discern this association." (PMID 19549343, 2009). "Epidemiological data on IGFs and IGFBP-3 for lung cancer, however, remain insufficient compared with those for breast, colorectal, and prostate cancers." (PMID 16127225, 2005). "Thus, IGFBP3 acts as a functional downstream target of FTO in regulating AKT activity in lung cancer." (PMID 40621649, 2025). "IGFBP3 in cancer has been studied predominantly in lung cancer but its role is still unclear." (PMID 40615716, 2025). "Notably, IGFBP-3 has been well-documented to show an inverse correlation with lung cancer, considering the lower levels of this IGFBP in the serum of patients vs. controls, as observed in several studies, suggesting it as a potential biomarker." (PMID 36902237, 2023). "Diminished survival of human lung cancer cells was correlated with increased expression of IGFBP-3." (PMID 36766747, 2023). "In addition, we recently reported that B-Myb can promote the activation of ERK and Akt signaling pathways through the inhibition of IGFBP3 in lung cancer." (PMID 34316028, 2021). "Increased expression of IGFBP‐3 corresponded with diminished survival of human lung cancer cells." (PMID 32592613, 2020). "In lung cancer, cisplatin-resistant cells exhibit reduced IGFBP3 expression." (PMID 32093285, 2020). "Furthermore, the hypermethylation of insulin-like growth factor-binding protein-3 (IGFBP-3) promotes cisplatin resistance in lung cancer." (PMID 32850327, 2020). "Dietary GSPE was also shown to target IGFBP-3 in lung cancer, and the specific mechanism may be related to the IGF-I/IGF-I receptor/IGFBP-3/phosphatidylinositol 3-kinase pathway." (PMID 33339407, 2020). "It is possible that both IGF‐1 and IGFBP‐3 contribute to the development of lung cancer." (PMID 27734632, 2016). "IGFBP-3 has been suggested as a potential target for lung cancer treatment, as adenovirus-mediated overexpression of IGFBP-3 inhibited the growth of NSCLC cells in vitro and in vivo by inducing apoptosis through the inhibition of the PI3K/Akt/PKB and MAPK signalling pathways." (PMID 24339922, 2013). "Evident fall of the circulating IGFBP-3 levels of the lung cancer patients was shown even though we couldn’t define the pattern and duration of the decline." (PMID 23185474, 2012). "We also evaluated the effect of IGF1, IGF2, and IGFBP3 (data not shown) on lung cancer risk by green tea consumption." (PMID 22347413, 2012). "The statistical power was not strong enough to demonstrate the relationship between IGFBP-3 concentration and lung cancer risk." (PMID 23185474, 2012).
lung carcinoma (continued). "The association between circulating IGF- I levels and the risk of lung cancer were not statistically significant; IGFBP-3, acts as a tumor suppressor and has a inverse correlation with the risk of lung cancer." (PMID 19549343, 2009). "An aetiological role for IGF-1 and IGFBP-3 in malignancy is supported by clinical studies that associate high IGF-1 and low IGFBP-3 levels with increased risk of several cancers, such as breast, colorectum, and lung cancer." (PMID 19570255, 2002). "Similarly, Patients with lung cancer have lower serum IGFBP3 levels." (PMID 36409444, 2022). "This study did not detect a protective effect of lower IGFBP3 levels overall; however, when one of the lung cancer cohorts was removed (that recruited only heavy smokers and asbestos workers), the risk of lung cancer was significantly decreased in individuals with higher IGFBP3 concentration." (PMID 31179642, 2019). "Thus, until now, there is little evidence for a link between IGF‐1 and lung cancer risk, but an inverse association between IGFBP‐3 and lung cancer risk has been observed." (PMID 27734632, 2016). "Therefore, the proportion of circulating IGFBP-3 secreted from lung cancer cells may be too small for the detection of significant changes related to the development of resistance, despite the loss of IGFBP-3 in lung cancer cells." (PMID 24339922, 2013). "In keeping with this speculation, we observed that heavy smokers with susceptible IGF1, IGF2, and IGFBP3 genotypes had an elevated risk of lung cancer, although the interaction effect was not significant." (PMID 22347413, 2012). "Inverse association was shown between IGFBP-3 and lung cancer in the case-control studies,and the circulating level of IGFBP-3 underwent a decline during tumorogenesis and development of lung cancer, which suggested IGFBP-3 a promising candidate for the biomarker of lung cancer." (PMID 23185474, 2012). "Based on our findings, we propose a model depicting regulation of cisplatin resistance in lung cancer cells by CK2, CD44, and IGFBP-3." (PMID 36766747, 2023). "Earlier, we published that IGFBP-3 binds HA through this 18-residue basic motif and blocks HA interactions with its receptor, CD44, reducing viability of A549 human lung cancer cells." (PMID 36428962, 2022). "NRF2 is considered a tumor suppressor, and HMOX1 its downstream effector to suppress lung cancer cells migration, via the transcriptional regulation of genes such as plasminogen activator urokinase (PLAU), MMP1, MMP9, and IGF binding protein-3 (IGFBP3)." (PMID 33537086, 2021). "Expression of IGFBP-3 led to increased cleaved caspase-3, inactivation of MAPK signaling, and corresponded with diminished survival of human lung cancer cells." (PMID 32193421, 2020). "Overexpression of IGFBP3 reduced migration and invasion by down-regulating PLAU in lung cancer cell lines H1299 and A54922." (PMID 31527696, 2019). "Of these, only IGFBP3 and SLFN11 were additionally tested in clinical tissue samples derived from NSCLC patients but still showed a rather poor predictive power in lung cancer." (PMID 30029672, 2018). "Here, we investigated IGFBP-3 expression in two EGFR mutant lung cancer cell lines with resistance to EGFR-TKIs and examined the value of serum IGFBP-3 level as a marker of resistance." (PMID 24339922, 2013). "In the present study, IGFBP-3 expression was examined in EGFR mutant lung cancer cells with acquired resistance to EGFR-TKIs, and the value of serum IGFBP-3 level was evaluated as a marker of resistance." (PMID 24339922, 2013).
lung carcinoma (continued). "Taken together, these findings support the hypothesis that FTO‐ and m6A‐mediated regulation of IGFBP3 leads to activation of the AKT pathway through an IGF‐independent mechanism, thereby contributing to lung cancer progression." (PMID 40621649, 2025). "Earlier, we published that IGFBP-3 binds HA through residues 215–232 in the C-terminal region of the protein and blocks HA interactions with its receptor, CD44, reducing viability of A549 human lung cancer cells." (PMID 36766747, 2023). "Among them, IGFBP2, IGFBP3, IGFBP4, IGFBP6 and IGFBP7 showed higher expression levels, especially in gastric, liver and lung cancer cell lines; conversely, IGFBP1, IGFBP5 and IGFBPL1 showed relatively lower expression, particularly in colorectal, gastric and kidney cancer cell lines." (PMID 37088808, 2023). "IGFBP-3 positively correlated with lower clinical stage, Ki-67 staining and grading, and the absence of necrosis and improved overall survival in lung cancer." (PMID 37510722, 2023). "The remaining two studies demonstrated no statistically significant tendency between IGFBP-3 and initiation of lung cancer." (PMID 35198099, 2022). "Lung cancer tissue contains differential expression of multiple molecules within the IGF axis, including the boosted production of IGF-I, IGF-II, and IGF-1 receptor (IGF-1R) and decreased expression of IGF binding protein-3 (IGFBP-3)." (PMID 35198099, 2022). "Although a reconciliation of the discrepancy presented in prior publications for IGF-I levels was not achieved, the consideration of IGFBP-3 as a potential biomarker for lung cancer was further supported." (PMID 35198099, 2022). "Biomarker research in recent years has shifted towards the use of IGFBPs outside of IGFBP-3, which may potentially widen the array of biomarkers within the IGF system for lung cancer detection." (PMID 35198099, 2022). "The roles of many of these binding proteins, however, are still incompletely described, and their significance as possible markers for lung cancer are not as well-documented as IGFBP-3." (PMID 35198099, 2022). "Previously, we found that IGFBP‐3 binds HA via amino acid residues 215–232 in the C‐terminal region of the protein (215‐KKGFYKKKQCRPSKGRKR‐232), blocking HA interactions with CD44 and reducing viability of A549 human lung cancer cells." (PMID 32592613, 2020). "Recently, we found that IGFBP-3 binds HA through residues 215–232 in the C-terminal region of the protein (215-KKGFYKKKQCRPSKGRKR-232) and blocks its interactions with CD44, reducing cell viability of A549 human lung cancer cells." (PMID 32193421, 2020). "We compared circulating levels of IGF-I and IGFBP-3 of lung cancer cases with that of controls, the results are the overall WMD = -3.04(95%CI: -7.10~1.02, P = 0.14) for IGF-I, and WMD = -112.28(95%CI: -165.88~-58.68, P < 0.0001) for IGFBP-3." (PMID 19549343, 2009). "Insulin-like growth factor-I (IGF-I) and IGF-binding protein-3 (IGFBP-3) have been widely accepted that they may have key role on the genesis and development of many types of tumor including lung cancer." (PMID 19549343, 2009). "There was no indication of an association between IGF-1 and lung cancer (OR=1.02 (0.80–1.31)) nor between IGFBP-3 and lung cancer (OR=0.98 (0.61–1.58))." (PMID 16804529, 2006). "Our previous studies showed that IGFBP-3 binds HA via the 18-residue basic domain, amino acid residues 215–232 (215-KKGFYKKKQCRPSKGRKR-232) in the C-terminal region of the protein, abolishing HA-CD44 interactions, and decreasing A549 lung cancer cell viability." (PMID 36766747, 2023). "In addition, IGFBP‐3 facilitated TGF‐β‐mediated EMT in esophageal and lung cancer cells." (PMID 32767843, 2020).